RAB1A (RAB1A, member RAS oncogene family)
Description:
The small GTPases Rab are key regulators of intracellular membrane trafficking, from the formation of transport vesicles to their fusion with membranes. Rabs cycle between an inactive GDP-bound form and an active GTP-bound form that is able to recruit to membranes different sets of downstream effectors directly responsible for vesicle formation, movement, tethering and fusion. RAB1A regulates vesicular protein transport from the endoplasmic reticulum (ER) to the Golgi compartment and on to the cell surface, and plays a role in IL-8 and growth hormone secretion. Required to modulate the compacted morphology of the Golgi. Regulates the level of CASR present at the cell membrane. Plays a role in cell adhesion and cell migration, via its role in protein trafficking. Plays a role in autophagosome assembly and cellular defense reactions against pathogenic bacteria. Plays a role in microtubule-dependent protein transport by early endosomes and in anterograde melanosome transport (By similarity).
Synonyms: RAB1; YPT1
Tractability: Small molecule: a structure with a bound ligand is known. PROTAC: UniProt records ubiquitination sites on it; ubiquitination databases record sites on it; its protein half-life has been measured.
Target class: Enzyme; Hydrolase
Gene: Protein-coding gene on chromosome 2 (65,070,696 to 65,130,986, reverse strand). Ensembl gene ENSG00000138069.
Subcellular location: Golgi apparatus; Endoplasmic reticulum; Early endosome; Cytoplasm, cytosol; Membrane; Melanosome
Subcellular location (Human Protein Atlas): Cytosol; Endoplasmic reticulum
Pathways (Reactome):
Vesicle-mediated transport: COPI-dependent Golgi-to-ER retrograde traffic; COPI-mediated anterograde transport; COPII-mediated vesicle transport; RAB GEFs exchange GTP for GDP on RABs
Cell Cycle: Golgi Cisternae Pericentriolar Stack Reorganization
Metabolism of proteins: RAB geranylgeranylation
Gene Ontology:
Molecular function: cadherin binding; G protein activity; GTPase activity; protein binding; GTP binding
Biological process: autophagosome assembly; autophagy; cell migration; cilium assembly; COPII-coated vesicle cargo loading; defense response to bacterium; endocytosis; endoplasmic reticulum to Golgi vesicle-mediated transport; establishment of endothelial intestinal barrier; Golgi organization; growth hormone secretion; positive regulation of glycoprotein metabolic process; positive regulation of interleukin-8 production; vesicle transport along microtubule; virion assembly; vesicle-mediated transport; melanosome transport; substrate adhesion-dependent cell spreading
Cellular component: cytosol; early endosome; endoplasmic reticulum; extracellular exosome; Golgi apparatus; membrane; Golgi membrane; melanosome; transport vesicle membrane; transport vesicle
Genetic constraint (gnomAD): Loss-of-function variants: 1 observed, 15.27 expected, observed/expected ratio (o/e) 0.0655, 90% interval 0.022 to 0.31. The upper end of that interval is the gene's LOEUF score, 0.31, which puts it in group 1 of 6, group 1 being the genes least tolerant of losing a copy. Missense variants: 86 observed, 192.12 expected, observed/expected ratio (o/e) 0.45, 90% interval 0.38 to 0.54. Synonymous variants: 72 observed, 70.9 expected, observed/expected ratio (o/e) 1.02, 90% interval 0.84 to 1.24.
Homologues: Orthologues: chimpanzee RAB1A (100% identical), guinea pig RAB1A (100% identical), mouse Rab1a (100% identical), rabbit RAB1A (100% identical), macaque RAB1A (97% identical), pig RAB1A (97% identical), dog RAB1A (96% identical), rat Rab1a (94% identical), Drosophila melanogaster Rab1 (85% identical). Paralogues in human: RAB1B (91% identical), RAB35 (55% identical), RAB8B (54% identical), RAB8A (53% identical), RAB10 (53% identical), RAB13 (50% identical), RAB12 (49% identical), RAB11A (46% identical), RAB18 (46% identical), RAB3C (46% identical), RAB11B (45% identical), RAB3B (45% identical), and 56 more.
Diseases named in the same sentence as RAB1A in open-access papers:
RAB1A is named in the same sentence as 72 diseases in open-access papers, as found by Europe PMC text mining. Sharing a sentence is not in itself a finding about the gene and the disease. The quoted sentences say what the papers report.
hepatocellular carcinoma (16 papers, 2015 to 2024). A malignant tumor that arises from hepatocytes. "RAB1A is overexpressed in 40 to 60% human colorectal and hepatocellular carcinomas, which is strongly associated with cancer progression and poor survival." (PMID 26590354, 2015). "MiR-634 has been reported to exhibit antitumor activities toward hepatocellular carcinoma via Rab1A and DHX33." (PMID 38704809, 2024). "Similar to GOLPH3, human Rab1A functions as an oncogene in breast cancer, colorectal carcinoma and hepatocellular carcinoma." (PMID 36435842, 2022). "For instance, USP2a, a deubiquitinating enzyme, stabilized RAB1A to promote cancer progression and metastasis in hepatocellular carcinoma." (PMID 36566018, 2022). "We aimed to characterize the roles of small GTPase activators of mTOR including RagC, Rab1A, Rab5, and Arf1 in senescence-like hepatoma cell line HepG2." (PMID 36267578, 2022). "Previous studies have reported an oncogenic function of Rab1A in colorectal cancer and hepatocellular carcinomas via the mTOR pathway." (PMID 31527621, 2019). "It has been found that miR-634 functions as a tumor suppressor in human hepatocellular carcinoma by down-regulating RAB1A." (PMID 29301870, 2018). "Importantly, Rab1A overexpression enhances AA-mTORC1 signaling in hepatocellular carcinomas, suggesting that aberrant AA signaling is a main driving event for hepato-oncogenesis." (PMID 26308575, 2015). "USP2a could promote hepatocellular carcinoma invasion via deubiquitinating RAB1A." (PMID 34489969, 2021). "In the previous studies, we demonstrated that Rab1A is overexpressed and associated with tumor prognosis in patients with CRC and hepatocellular carcinoma (HCC), promoting tumor growth and metastasis through activating mTORC1 signaling." (PMID 28316326, 2017). "Recently, Rab1A has been validated to be a pivotal oncogene that promotes the progression and metastasis of colorectal cancer (CRC) and hepatocellular carcinoma (HCC) by activating mTORC1 signaling." (PMID 33068388, 2020). "Rab1A has been identified as a colorectal oncogene, and elevated expression of Rab1A has been reported in multiple cancer types, including colorectal cancer (CRC), hepatocellular carcinoma (HCC), glioma, prostate cancer, tongue squamous carcinoma and cervical cancer." (PMID 27902464, 2016). "Overexpression of RAB1A and RAB1B is found in colorectal cancer (CRC) and hepatocellular carcinoma (HCC), as well as several other cancer types including tongue squamous carcinomas (TSCCs)." (PMID 26590354, 2015). "Moreover, because increased expression of either RAB1A or RAB1B has been found in several types of cancer, including prostate cancer, hepatocellular carcinoma and colorectal carcinoma, it would be not surprising if their effects are synergistic with that of overexpressed GOLPH3." (PMID 32790781, 2020).
colorectal cancer (14 papers, 2015 to 2025). A primary or metastatic malignant neoplasm that affects the colon or rectum. "Previous studies have shown that RAB1A is elevated in the progression of human cancers and associated with a poor prognosis in patients with cancers such as lung cancer, colorectal cancer, intrahepatic cholangiocarcinoma, gastric cancer, and bladder cancer." (PMID 39771598, 2024). "According to the study by Thomas, Ras-related protein Rab-1A (RAB1A) overexpression positively correlates with mTOR activation and rapamycin sensitivity in colorectal cancer cell lines." (PMID 41050665, 2025). "Given previous reports of RAB1A-mediated mTOR regulation in colorectal cancer, we downregulated RAB1A expression of two human PCa cell lines with RAB1A-targeting shRNA lentiviruses." (PMID 41050665, 2025). "Numerous investigations have provided evidence that abnormal RAB1A expression is a common occurrence in human cancers, such as colorectal cancer, GC, bladder cancer, HCC, breast cancer, and nasopharyngeal cancer." (PMID 39771598, 2024). "For example, Rab1a is upregulated in colorectal cancer, and Rab3d is overexpressed in a series of tumors including breast and lung cancer." (PMID 35910358, 2022). "The role of Rab1A in colorectal cancer (CRC) has been described in previous studies, but the molecular mechanisms of Rab1A in CRC remain far from being addressed." (PMID 34376787, 2021). "(A) Cluster analysis of 135 pairs of colorectal cancer (green) and normal tissues (red) based on Rab1A and FoxM1 IHC scores." (PMID 33214609, 2020). "We found that the expression of Rab1A and FoxM1 was significantly higher in colorectal cancer tissues than in normal tissues (P < 0.001, P < 0.001)." (PMID 33214609, 2020). "For example, Rab1a overexpression in colorectal cancers is correlated with the mammalian target of rapamycin complex 1 (mTORC1) activation in tumors and this occurs through a direct interaction between Rab1a and mTORC1." (PMID 31973201, 2020). "First, immunohistochemistry (IHC) staining was performed in 135 pairs of colorectal cancer and adjacent normal tissues to detect Rab1A and FoxM1 expression." (PMID 33214609, 2020). "Because Rab1A has been reported to be correlated with hyperactive mTORC1 signaling in human colorectal cancer, we examined whether Rab1A expression was correlated with mTORC1 signaling in lung cancer." (PMID 27902464, 2016). "Rab1A was previously reported to be an oncogene in human colorectal cancer, however, the effect on colon cancer apoptosis was not clear." (PMID 26023735, 2015).
glioma (10 papers, 2016 to 2023). A benign or malignant brain and spinal cord tumor that arises from glial cells (astrocytes, oligodendrocytes, ependymal cells). "Previous studies have shown that some Rab proteins such as Rab1a, Rab21, and Rab26 are closely associated with the development and progression of many tumors, including glioma." (PMID 36922509, 2023). "Furthermore, we found RAB1A was up-regulated in glioma tissue samples and positively associated with the expression of DANCR." (PMID 29301870, 2018). "In cancer development, abnormal expression of RAB1A is involved in the progression of various cancers, such as colon cancer, tongue cancer, and glioma in humans, all of which exhibit some degree of cancer-promoting effects in a gene dose-dependent manner." (PMID 36476239, 2022). "In glioma, the miR-1202 expression is inversely correlated with the expression of Ras-related protein Rab-1A (RAB1A)." (PMID 32101576, 2020). "Results showed that DANCR inhibition suppressed RAB1A expression in glioma cells both at mRNA and protein levels, and miR-634 inhibitor restored the reduction of RAB1A expression in DANCR suppressed glioma cells (P<0.05)." (PMID 29301870, 2018). "Our study discovered a novel mechanism that DANCR served as a molecular sponge for miR-634 and regulated RAB1A in glioma progression." (PMID 29301870, 2018). "DANCR could directly interact with miR-634 in glioma cells and this interaction results in the inhibition of downstream of RAB1A expression." (PMID 33123287, 2020). "For instance, DANCR regulated RAB1A expression in glioma by functioning as a ceRNA of miR-634." (PMID 32099526, 2020). "For example, lncRNA DANCR may act as a competing endogenous RNA to regulate Ras-related protein RAB1A expression by sponging miR-634 in glioma." (PMID 31216644, 2019). "Additionally, we determined the expression of RAB1A in glioma tissue samples by qRT-PCR, results showed that RAB1A expression was significantly increased and positively associated with DANCR expression in glioma tissues (P<0.05)." (PMID 29301870, 2018). "The present study demonstrated that DANCR/miR-634/RAB1A axis plays crucial roles in the progression of glioma, and DANCR might potentially serve as a therapeutic target for the treatment of glioma patients." (PMID 29301870, 2018). "To determine whether DANCR could function as a ceRNA for RAB1A via modulating miR-634 in glioma, we determined the mRNA and protein levels of RAB1A after glioma cells transfected with si-DANCR combined with miR-634 inhibitor." (PMID 29301870, 2018). "Taken together, these results indicated that DANCR could act as a sponge for miR-634 to up-regulate the expression of RAB1A in glioma." (PMID 29301870, 2018). "In addition, we verified that DANCR could directly interact with miR-634 in glioma cells and this interaction resulted in the inhibition of downstream of RAB1A expression." (PMID 29301870, 2018). "However, the interaction between lncRNA and RAB1A in glioma remains unclear." (PMID 29301870, 2018). "In the present study, our data showed that DANCR inhibition suppressed RAB1A expression in glioma cells, and miR-634 inhibitors restored the reduction of RAB1A expression in DANCR suppressed glioma cells." (PMID 29301870, 2018). "Elevated levels of Rab1A DNA, mRNA or protein have been reported previously in human CRC, gliomas, HCC, prostate cancer and tongue squamous carcinomas." (PMID 27902464, 2016).
lung carcinoma (9 papers, 2016 to 2024). "Rab1A expression is associated with malignant phenotypes in several human tumors; however, the role of Rab1A in lung cancer is still unclear." (PMID 27902464, 2016). "In light of the present data considered in the context of previous findings, we can hypothesize that Rab1A overexpression is associated with clinical pathological parameters of human lung cancer." (PMID 27902464, 2016). "Upregulation of Rab1a expression in lung cancer cells enhances cell mobility including migration, invasion and metastasis both in vitro and in vivo through activating JAK1/STAT6 signaling pathway in an IL-4Rα dependent manner." (PMID 38695990, 2024). "For different histological subtypes of lung cancer, Rab1A showed similar expression patterns with a 100% positive staining rate in adenocarcinoma, adenosquamous carcinoma and large cell lung cancer tissues." (PMID 27902464, 2016). "In this study, we investigated Rab1A expression in tissues and cell lines from different lung cancer subtypes, and assessed the relationships between Rab1A expression and clinical parameters as well as key cancer cell signaling pathways." (PMID 27902464, 2016). "The mechanisms by which Rab1A overexpression contributes to lung cancer, including cell cycle progressing and promoting migration and metastasis, are under investigation." (PMID 27902464, 2016). "In a large panel of lung cancer cell lines, high Rab1A expression was observed as compared to a normal lung/bronchus epithelial cell line." (PMID 27902464, 2016). "Furthermore, RAB1A, a homolog of RAB1B, was proven to be upregulated in lung cancer and associated with T stage." (PMID 32710726, 2020). "We further examined Rab1A expression in a panel of lung cancer cell lines." (PMID 27902464, 2016). "In this study, we attempted to establish the role of Rab1A in major human lung cancer subtypes." (PMID 27902464, 2016). "It would be of interest to investigate whether Rab1B, a paralog of Rab1A, could play a major role in mTOR regulation in lung cancer." (PMID 27902464, 2016). "Compared with the immortalized lung/bronchus epithelial cell line BEAS-2B, Rab1A is highly expressed in all lung cancer cell lines with great variability, ranging from a 6-fold increase in the A549 and H1650 cell lines to a 1.5-fold increase in H460 and SK-LU-1 cells lines." (PMID 27902464, 2016). "Here we report that Rab1A overexpression is correlated with tumor volume and stage in lung cancer." (PMID 27902464, 2016). "Our study for the first time shows that Rab1A is significantly overexpressed in lung cancer." (PMID 27902464, 2016). "In addition, in lung cancer, Rab1A expression levels were not correlated with histological type; different lung cancer subtype tissues and cell lines all showed significant Rab1A overexpression, suggesting that aberrant Rab1A expression is universal in lung cancers." (PMID 27902464, 2016). "Therefore, we examined whether Rab1A knockdown had similar effects in human lung cancers." (PMID 27902464, 2016). "Further verification of RAB1A and TM9SF3, whether they are highly expressed in lung cancer patients." (PMID 36101742, 2022). "Despite the importance of Rab1A in human malignancies, to date, Rab1A has not been studied in the context of lung cancer." (PMID 27902464, 2016). "The results demonstrated that Rab1A was significantly overexpressed in the different histological types of lung cancer as compared to non-cancerous tissues, and Rab1A expression was correlated with tumor volume and stage." (PMID 27902464, 2016). "Immunohistochemical staining was performed to evaluate Rab1A expression in 60 lung cancer tissues and paired adjacent noncancerous tissues." (PMID 27902464, 2016). "Compared with matched noncancerous tissues (median H score = 15), Rab1A staining was much stronger in lung cancer tissues (median H score = 189)." (PMID 27902464, 2016).
lung carcinoma (continued). "In addition, Rab1A is found to be a determinant sensitivity of JAK1 inhibitor, suggesting that JAK1 inhibitor could be potential therapeutics for lung cancer metastasis." (PMID 38695990, 2024). "Rab1A expression in different histological types of human lung cancer was analyzed in lung cancer tissues with paired adjacent noncancerous tissues and a large panel of lung cancer cell lines." (PMID 27902464, 2016).